IL1B (interleukin 1 beta)
Diseases named in the same sentence as IL1B in open-access papers (continued):
Sharing a sentence is not in itself a finding about the gene and the disease.
breast tumor (continued). "Analysis revealed a significant up-regulation in the expression of genes from the NLRP3 inflammasome pathway (NLRP3, PYCARD, CASP1, and IL-1β) in the stroma of human breast tumours compared with normal stroma, suggesting a functional role for this pathway in tumour progression." (PMID 31558756, 2019). "The fact that aggressive IRISOE TNBC cells produce and secrete high-level IL-1β in HIF-1α and NF-κB-dependent manner is consistent with recent reports showing IL-1β is a critical mediator of inflammation leading to tumor progression within breast tumor microenvironment." (PMID 29262555, 2017). "TNF-α and IL-1β are highly relevant to the inflammatory setup of breast tumors." (PMID 25928089, 2015). "Such a cross-talk may lead to up-regulated expression of CCL2 and CCL5 in tumors expressing TNFα and/or IL-1β, thus possibly leading to increased tumor-supporting activities of the two chemokines in breast tumors (see Discussion, below)." (PMID 21486440, 2011). "The promoter analysis of IL1B, CDH13, and PTPN11, using SMART App, showed methylation status in breast tumor patient samples." (PMID 36474139, 2022). "On the other hand, the stimulation of macrophages to secrete pro-inflammatory factors such as IL-1b, IL-6, and TNF-α by exosomal transfer of miR-183 led to tumor growth and metastasis of the 4T1 breast tumor model in vivo." (PMID 36012638, 2022). "Our data demonstrated MMP-7 activation in human epithelial cells after treatment with IL-1β or TNFα and are supported by publications showing that MMP-7 is secreted by colon and breast tumors, which are primarily epithelial cells." (PMID 36275703, 2022). "As seen in macrophages and HEK293 cells, knockdown of RAS clearly suppressed the levels of IL-1β and TNF-α in breast tumor cells." (PMID 32422978, 2020). "Here, the authors show that CAFs sense tissue damage and activate NLRP3 inflammasome and pro-inflammatory IL-1β secretion, and CAF-derived inflammasome signalling promotes breast tumour growth and metastasis." (PMID 31558756, 2019). "Secretion of multiple cytokines including IL-6, IL-12, IL-1β and TNF-α from DCs was measured by ELISA Kit after transwell co-culture (diffusion model) or direct co-culture of immature DCs with the ablated breast tumor cells (cell contacting model) for 24 h." (PMID 30583459, 2018). "Similarly, Sosnoski and colleagues found that IL-1β and TNF-α broke the dormant state of breast tumour cells induced by osteoblasts in their coculture system." (PMID 36307871, 2022). "Furthermore, blocking IL-1β can reduce the recruitment of monocytes mediated by CCL2, decrease the infiltrating macrophages in the tumor microenvironment, and prevent breast tumor growth." (PMID 36403055, 2022). "We did not detect IL1β mRNA in the MCF7 or T47D breast tumor cell lines, whereas TGFβ and TNFα were detected in these cells, highlighting a potential paracrine effect of these two effectors on breast APCs." (PMID 36009475, 2022). "Yet, the impact of persistent proinflammatory stimulation on breast tumor cells was not investigated in depth, leading us to determine the effects of continuous TNFα + IL-1β stimulation on TNBC cell characteristics and functions." (PMID 34072893, 2021). "In our analysis of the TCGA breast tumor cohort, we observed significant positive correlations between TREM1 expression and the expression of TREM-1 target cytokines (IL1B, IL8, IL6 and CCL2) and markers of MDSCs and TAMs (CD11B/ITGAM, OLR1, CD14 and CD206/MRC1)." (PMID 34956864, 2021). "IL1B, IL6, TNF, IL8 and CXCR4 mRNA levels were significantly increased in the high AHR-expressing ERα-negative breast tumor subpopulation, while these associations were only observed for IL6 and CSF1 in the ERα-positive tumor subgroup." (PMID 29320557, 2018).
breast tumor (continued). "As IL-1β and LCN2 appear to promote breast tumour malignancy and lead to a poorer prognosis, we speculate that β-hydroxybutyrate induced upregulation of their expression might contribute to the observed increased tumorigenesis." (PMID 28281525, 2017). "Indeed, our findings and published studies indicate that TNFα and IL-1β up-regulate the release of CCL2 and CCL5 by breast tumor cells." (PMID 21486440, 2011). "To examine, whether different sources of fibroblasts can also secrete IL1β in co-cultures through similar mechanisms, MCF7 and T47D cells were placed in co-cultures with fibroblasts obtained from primary ER+ human breast tumor adjacent tissue (TAT-Fs), CNTB-Fs, and NAFs." (PMID 31419632, 2019). "Finally, lower levels of several pro-inflammatory cytokines (IL1B, IL10, IL12, IL6, IL8, TNF), NK cell metagenes (NCR1, XCL1), cytolytic enzymes (GZMA, GZMB, PRF) and type I IFN-induced genes were also observed in IL-1R8 high breast tumors." (PMID 28533483, 2017). "Interestingly, breast tumor-bearing mice on anti-CTLA4 therapy when placed on a low-salt diet demonstrated decreased peripheral circulatory levels of inflammatory cytokines (IFNγ and IL-1β) and reduced lung infiltrating of inflammatory immune cells along with reduced tumor progression." (PMID 40563574, 2025). "Two well-known ligands for AHR (TCDD and BaP) induced mRNA expression of IL1B and IL6 in an ERα-negative breast tumor cell line." (PMID 29320557, 2018). "This lack of coordination between CCL2 & CCL5 and TNFα & IL-1β in this sub-population is intriguing mainly because TNFα and IL-1β were found to stimulate the release of CCL2 and CCL5 by breast tumor cells." (PMID 21486440, 2011). "Although the expression of TNFα & IL-1β receptors by breast tumor cells was already documented, it is possible that in this specific sub-group of the IDC-with-recurrence patients, the tumor cells do not express the required receptors for TNFα & IL-1β, or express non-signaling receptors." (PMID 21486440, 2011).
oral cancer (53 papers, 2007 to 2026). "IL-8 and IL-1β, cytokines implicated in processes such as replication, angiogenesis, and tumor development, are particularly relevant in oral cancer diagnosis." (PMID 39200213, 2024). "Dong and Pires developed a microfluidic biosensor based on absorbance for the multiplexed detection of three salivary biomarkers commonly associated with oral cancer, IL-8, IL-1β and MMP-8." (PMID 34677352, 2021). "Altered immunity can cause commensal microorganisms to become pathogenic and induce high levels of oncogenic IL-1β for oral cancer." (PMID 33120999, 2020). "Cytokine concentrations were measured by commercial enzyme linked immunoassay.Results: Salivary IL-1β and IL-6 were significantly higher in oral cancer patients than in patients with leukoplakia and control group (p<0.05)." (PMID 21743397, 2012). "Notably, alcohol consumption appears to accelerate the increase in IL-1β levels more rapidly compared to other oral cancer risk factors." (PMID 39200213, 2024). "Therefore, the observed elevation in IL-1β levels in smokers could be indicative of the underlying inflammatory processes contributing to the pathogenesis of oral cancer." (PMID 39200213, 2024). "Cancer-associated fibroblast-secreted IL-1β may activate CCL22 signaling in oral cancer." (PMID 35860473, 2022). "These macrophages play a crucial role in oral cancer development by releasing pro-inflammatory cytokines such as IL-1β and IL-8." (PMID 39200213, 2024). "As a consequence, several groups investigated the biomarker role of interleukins in several phases of oral cancer progression, and IL-1-β, IL-6, and IL-8 resulted in potentially predictive salivary biomarkers of OSCC progression." (PMID 36412636, 2022). "A recent report demonstrated that IL-1β produced by CAFs induces CCL22 mRNA overexpression in oral cancer cells." (PMID 35048046, 2021). "A study showed that a combination of several salivary biomarkers (proteins such as thioredoxin and IL-8 and mRNAs such as SAT, ODZ, IL-8, and IL-1b) are able to detect oral cancer with high specificity and sensitivity." (PMID 34359370, 2021). "The results have revealed the potential of specific deregulated cytokines, such as IL-1β, IL-6, and IL-8, as predictive salivary biomarkers for the early diagnosis of oral cancer." (PMID 33120999, 2020). "The serum levels of Il-1β, Il-6 and Tnf-α are higher in patients with oral cancer than in healthy subjects." (PMID 25050571, 2014). "Serum IL-1β concentrations were below the level of detection in all three groups of participants, except in one patient with oral cancer and one control participant." (PMID 21743397, 2012). "Concentrations of salivary IL-1β were significantly higher in oral cancer patients than in patients with leukoplakia and control group (p≤0.05)." (PMID 21743397, 2012). "Results of this study show that patients with oral cancer have higher salivary IL-1β and IL-6 concentrations compared to patients with leukoplakia and healthy controls." (PMID 21743397, 2012). "Our results show that patients with oral cancer have significantly higher concentrations of salivary IL-1β and IL-6 compared to patients with leukoplakia and healthy individuals." (PMID 21743397, 2012). "Profiling of salivary mRNA indicated four major biomarkers of oral cancer including interleukin-1-β (IL1β), interleukin-8 (IL8), ornithine decarboxylase antizyme-1 (OAZ1) and spermidine/spermine N1-acetyltransferase (SAT)." (PMID 19424479, 2008). "Hence, over 100 potential biomarkers for detecting oral cancer have been observed, with IL-8 and IL-1β playing crucial roles in cell replication, angiogenesis, cell adhesion, and tumor development." (PMID 39200213, 2024). "The present study uncovered differences in salivary IL-1β concentrations between individuals with and without habits linked to oral cancer risk." (PMID 39200213, 2024). "Further, higher expression of CTSC, HIF1A, and IL1B was observed in both stages of oral cancer." (PMID 38234400, 2023).
oral cancer (continued). "Oral cancer has been linked to pro-inflammatory cytokines, such as CXCL1 and IL-1β." (PMID 35626430, 2022). "IL-1β levels were found to be higher in oral cancers in previous studies." (PMID 35626430, 2022). "IL-1β is overexpressed in the saliva of oral cancer patients compared to oral leukoplakia and control patients and IL-1β salivary levels have been shown to discriminate between OSCC subjects and controls, but not between oral potentially malignant disorder (OPMD) patients and healthy subjects." (PMID 35048046, 2021). "Our previous studies have revealed that IL-1β plays a major role in oral cancer tumorigenesis." (PMID 33668218, 2021). "When treated with ZYM, OSCC cells secreted significantly more pro-inflammatory cytokine IL-1β, which could enhance inflammation in oral cancer microenvironment." (PMID 32760436, 2020). "Moreover, IL-1β transactivates the epidermal growth factor receptor through the CXCL1–CXCR2 axis in oral cancer." (PMID 33120999, 2020). "However, the animal model experiment of 4NQO-induced rat oral cancer proved that IL-1β changed tumor microenvironment and inhibited cell proliferation in gene silenced (LV-shIL-1β) tumor cells." (PMID 32577124, 2020). "Whether the increase of salivary IL-1β and IL-6 happens before oral cancer becomes clinically evident and whether it could be used for monitoring the malignant transformation of oral leukoplakia remains to be answered by further studies." (PMID 21743397, 2012). "Thus, Basak and coworkers used an FDA-approved, turmeric-derived, curcumin-based formulation, APG-157DS, in a placebo-controlled human trial for oral cancer to demonstrate a reduction in pro-tumor cytokines IL-1β, IL-6, and IL-8 in the salivary supernatant fluid of patients with cancer." (PMID 41227348, 2025). "In addition, an association between IL-1β and CXCR2 has been reported in oral cancers." (PMID 35626430, 2022). "A previous study showed that IL‐1β could activate EGFR via the CXCL1‐CXCR2 axis in oral cancers." (PMID 33955688, 2021). "In oral cancer, elevated NLRP3 and IL-1β expression frequently correlate with tumor progression, largely driven by mitochondrial dysfunction, impaired autophagy, and alterations in the tumor-associated microbiota." (PMID 41596738, 2026). "Consistently, a recent systematic review reported elevated salivary concentrations of IL-1β, IL-1α, IL-8, IL-6, and TNF-α in patients with oral cancer when compared with healthy controls." (PMID 41440367, 2025). "This study observed that IL-37 exhibited potent inhibitory effects on the TNF-α-induced expression of inflammation-related genes, including IL23, IL1b, IL6, and IL17 in oral cancer cells." (PMID 40444012, 2025). "Several studies have detected IL-1β and IL-8 in the serum and saliva (IL-1β 0.5–12 pg/mL; IL-8 < 62 pg/mL) of patients with oral squamous cell carcinoma (OSCC), highlighting their significance as biomarkers for oral cancer." (PMID 39200213, 2024). "The four salivary mRNAs, (IL1b, IL8, SAT, and OAZ) together exhibited 91% specificity and sensitivity for detecting oral cancer, underscoring the usefulness of salivary transcriptome diagnostics in detection of oral cancer." (PMID 38522008, 2024). "In an in vitro model employing OSCC cells and an in vivo xenograft model of oral cancer, an NLRP3 inflammasome inhibitor BAY-117082 significantly reduced NLRP3, ASC, caspase-1, IL-1β, and IL-18 expression and a reduction in tumor growth." (PMID 38904007, 2024).
oral cancer (continued). "Endothelin-1 represents a potential biomarker for the development of OSCC in patients with oral lichen planus and IL-8, IL-1β, glycoprotein M2BP (Mac-2 binding protein), CD59, myeloid protein 14 (MRP14) and catalase as salivary biomarkers of oral cancer." (PMID 36412636, 2022). "IL-1R1 promotes oral cancer growth and metastasis by upregulating CXCR4 (a chemokine receptor involved in tumor progression, angiogenesis and metastasis) after IL-1β stimulation, and IL-1R1 inhibition with recombinant IL-1RA has shown to reverse these effects." (PMID 35048046, 2021). "In summary, the fungal cell wall component zymosan promoted OSCC proliferation, IL-1β production and C. albicans adhesion to OSCC in this study, providing information to better understand the interaction between C. albicans and oral cancer." (PMID 32760436, 2020). "The secretion of various cytokines including IL-1b, VEGF, and IL17 was reported to be increased in blood neutrophils in oral cancer, while the secretion of IL-18 and sTRAIL was reduced." (PMID 33162980, 2020). "The aim of this study was to compare salivary and serum concentrations of IL-1β, IL-6 and TNF-α in patients with oral leukoplakia, oral cancer and healthy controls." (PMID 21743397, 2012). "In most cases, pro-inflammatory cytokines (IFN-γ, IL-2, IL-1α, IL-1β, TNF-α, IL-17, and IL-8), anti-inflammatory cytokines (IL-4 and IL-10), and pro-/anti-inflammatory cytokines (IL-6 and TGF-β) are unbalanced in oral cancer, resulting in an immunosuppressive environment." (PMID 37686542, 2023). "Elevated expression of proinflammatory genes like s100a9, IL23a, IL1b, and immune checkpoint gene PDCD1/PD1 was reported during oral cancer development in the 4-NQO–induced cancer group in comparison to normal mice, and similar results have also been found in human oral cancer and other cancers." (PMID 37936711, 2023). "The pro-inflammatory cytokine, IL-1B, is elevated in HNSCC including oral cancer." (PMID 32961854, 2020). "Furthermore, DFO acted additively with IL-1β to up-regulate IL-8 in IHOK cells but not in oral cancer cells." (PMID 17850672, 2007).
brain inflammation (51 papers, 2010 to 2025). "Systemic IL-1β can cause CNS inflammation once it enters the brain, thus linking systemic inflammation and immune activation with brain inflammation." (PMID 31632307, 2019). "We have found that gestational low-protein diet (LPD) combined with IL-1β injection in rat pups (modeling intrauterine growth restriction and perinatal brain inflammation in human neonates) was associated with a selective down-regulation of mGlu3 receptors in microglia." (PMID 34220677, 2021). "In order to check whether brain inflammation was associated with an enhancement in peripheral inflammatory factors, IL-1β concentration was monitored in RBCs, which are able to produce cytokines, too." (PMID 31281579, 2019). "Notably, in contrast to the brain inflammation model investigated by Horai and colleagues, we observed a normal postoperative upregulation of either IL-1α or IL-1β in the ME of IL-1β- or IL-1α-deficient mice, respectively." (PMID 31332247, 2019). "Indeed, although limited, data in literature indicate that in both acute (i.e., ICV injection of cytokine) and chronic (i.e., EAE and AD transgenic model) paradigms of brain inflammation, IL-1β is still linked to LTP expression, whereas TNF seems to affect both LTP and synaptic scaling." (PMID 29861718, 2018). "The study found that in CSF1R mutant mice, the levels of inflammatory cytokines (such as IL-16 and IL-1β) were significantly elevated, indicating that microglial activation and pro-inflammatory responses exacerbate brain inflammation." (PMID 40893935, 2025). "Another study pointed out that the OA2 microglial cell subset promotes age-related brain inflammation by expressing some unique inflammatory signals (such as Lgals3 Cst7 Ccl4 Ccl3 Il1b)." (PMID 39440247, 2024). "TNF-α, IL-1β, and IL-6 are involved in the progression of brain inflammation through inducing the expression of chemokines that facilitate the infiltration of leukocytes into the CNS." (PMID 34765767, 2021). "Brain inflammation often involves expression of IL-1β, IL-6, IL-8, TGF-β1, and TNF-α, thus we started our screening experiments with these commercially available inflammatory factors." (PMID 33013631, 2020). "IL-1β in serum of dogs with inflammatory brain disease and brain tumor showed the mean values, SD and the range of 134.9 ± 79.2 (48.0–237.0) pg/mL and 154.2 ± 93.7 (37.5–308) pg/mL, respectively." (PMID 31208341, 2019). "It is noteworthy that TNFα and IL-1β, two important “ON” signals, are both primary pro-inflammatory cytokines that are upregulated in the context of brain inflammation." (PMID 31632307, 2019). "This decrease resulted in the attenuation of ICH-induced brain inflammation, evaluated by western blot to IL-1β." (PMID 29138419, 2017). "We have showed that IL-1β, the brain inflammation model we applied, stimulated the production of SDF-1, and both IL-1β and SDF-1 can induce NPC migration." (PMID 23210607, 2012). "We adapted a brain inflammation model with IL-1β injection and determined that IL-1β mediated NPC migration through chemokines SDF-1 and MCP-1." (PMID 23210607, 2012). "Consequently, patients and BM pigs with LHI experienced a marked increase in brain inflammation, manifested by a significant increase in the mRNA levels of inflammatory factors Il-1β and Tnf-α in the brain." (PMID 39071180, 2024). "Receptor NPC IL-1β is involved in reducing neurogenesis in murine models of brain inflammation." (PMID 36672177, 2023). "The same test was used to compare IL-1β serum levels in healthy dogs to those of the dogs with idiopathic epilepsy, inflammatory brain disease and brain tumors, and each group had higher IL-1β levels than controls regardless of the underlying cause of the seizures (p = 0.0045)." (PMID 31208341, 2019). "Furthermore, LPS-induced brain inflammation is accompanied by neuronal loss and microglia activation, which induce the release of neurotoxic factors, such as inflammatory cytokines (TNF-α, IL-1β, PGE2, etc.)." (PMID 30962497, 2019).